OR11L1 (olfactory receptor family 11 subfamily L member 1)
Description:
Odorant receptor.
Tractability: Antibody: UniProt places it where antibodies can reach, with medium confidence; UniProt predicts a signal peptide or a membrane-spanning region; its Gene Ontology location is reachable by antibodies, with medium confidence.
Gene: Protein-coding gene on chromosome 1 (247,840,928 to 247,841,896, reverse strand). Ensembl gene ENSG00000197591.
Subcellular location: Cell membrane
Pathways (Reactome):
Sensory Perception: Expression and translocation of olfactory receptors
Gene Ontology:
Molecular function: odorant binding; olfactory receptor activity; G protein-coupled receptor activity
Biological process: sensory perception of smell; detection of chemical stimulus involved in sensory perception of smell; G protein-coupled receptor signaling pathway
Cellular component: extracellular exosome; plasma membrane; membrane
Genetic constraint (gnomAD): Loss-of-function variants: 0 observed, 0.27 expected, observed/expected ratio (o/e) 0, 90% interval 0 to 1.87. That is too few expected variants to judge how well the gene tolerates losing a copy. Missense variants: 397 observed, 412.25 expected, observed/expected ratio (o/e) 0.96, 90% interval 0.89 to 1.05. Synonymous variants: 164 observed, 168.35 expected, observed/expected ratio (o/e) 0.97, 90% interval 0.86 to 1.11.
Homologues: Orthologues: macaque OR11L1 (89% identical), pig OR11L1 (77% identical), mouse Or11l3 (77% identical), rat Or11l3 (75% identical), rabbit OR11L1 (74% identical), guinea pig OR11L1 (72% identical). Paralogues in human: OR6Q1 (46% identical), OR8H1 (46% identical), OR6P1 (45% identical), OR8H2 (44% identical), OR5A1 (43% identical), OR6B3 (43% identical), OR8H3 (43% identical), OR6B2 (43% identical), OR9H1 (42% identical), OR5D18 (42% identical), OR5I1 (42% identical), OR8J1 (42% identical), and 84 more.